HMGB1 (high mobility group box 1)
Diseases named in the same sentence as HMGB1 in open-access papers (continued):
Sharing a sentence is not in itself a finding about the gene and the disease.
tumor (continued). "Based on HMGB1's known role as an alarmin that can induce danger signaling through RAGE and various TLR, it is interesting to speculate that TIM‐3‐mediated sequestration of HMGB1 might also prevent direct immunostimulatory signaling from this molecule in tumor‐associated DC." (PMID 32508018, 2020). "A study of PTC revealed that HMGB1 knockdown inhibited cell proliferation and metastasis in PTC cells in vitro and restrained xenograft tumor growth in vivo." (PMID 33817244, 2020). "We performed immunofluorescence analysis to study the expression of HMGB1, CRT, and CD8+ T cells in the tumour tissues after different treatments." (PMID 33009382, 2020). "Other important stress signals (ATP, HMGB1, and type I IFN) released by tumor cells are also important in triggering immunogenic cell death." (PMID 32911646, 2020). "These tumor cells produce stress-induced ligands (DAMPs): CALR, ATP, ANXA1, and HMGB1, whose activation is conditioned by several constraints." (PMID 33281620, 2020). "In the tumor sections of TNBC patients, in the tumor center, HMGB1 was located in the cytoplasm, while in the tumor margin, HMGB1 was located in the nucleus." (PMID 32943604, 2020). "HMGB1 combined with Tim-3 induces the secretion of angiogenic vascular endothelial growth factor (VEGF) and promotes tumor angiogenesis." (PMID 32660524, 2020). "MicroRNA-1179 interacted with the 3′ UTR of HMGB1 and suppressed HMGB1 expression at the post-transcriptional level and indicates that the microRNA-1179/MHGB1 pathway plays a tumor suppressor role in PTC." (PMID 33113852, 2020). "Free OLE is internalized into tumour cells and induces ICD through the release of HMGB1 from the dying cells." (PMID 33009382, 2020). "Pancreatic microenvironment is abundant in TLR4 ligands, including HMGB1 and S100A9, that can activate TLR4 signaling in tumor cells." (PMID 32516941, 2020). "This cancer-associated tissue injury is perpetuated by the homeostatic inflammatory and tissue repair responses, leading to High Mobility Group Box 1 (HMGB1) release, being this the most abundant DAMP released by the stressed tumor cells." (PMID 33604297, 2020). "Moreover, lncR-C3orf35 and HMGB1 may affect immune cell infiltration and tumor metastasis." (PMID 33015161, 2020). "Serum levels of the RAGE ligands, S100B, and HMGB1 also were robustly increased in LLC‐bearing compared with untreated mice, likely released from tumour cells." (PMID 32159297, 2020). "The RAGE (receptor for advanced glycation end-products) and its ligands, high mobility group box 1 (HMGB) and S100B have documented roles in skeletal muscle and in tumor." (PMID 33291708, 2020). "The authors contend that “HMGB1 release is a critical mechanism in hepatic pathogenesis under autophagy conditions and leads to HPC expansion as well as tumor progression”." (PMID 32664328, 2020). "A pilot of study indicated that the expression of HMGB1, calreticulin, and HSP70 in tumor cells increased significantly as the levels of electric field strength increased." (PMID 32508058, 2020). "As outlined in the previous section, not only does HMGB1 bind platelets via TLR4, it also activates TLR9-dependent pathways in cancer cells, thereby promoting tumor cell proliferation, adhesion, migration and invasion after surgical stress." (PMID 33353113, 2020). "As is shown in the multi-colour immunofluorescence staining analysis of 135 GC tissues, ~90% of tissues show that NECTIN2, CEACAM1, HMGB1, SIGLEC6 and CD15 were expressed in tumour cells, and CD44 was expressed in tumour cells in about 70% of tissues." (PMID 33311518, 2020). "Co-immunofluorescence staining also showed that tumor cells with accumulated SQSTM1 were also devoid of both nuclear and cytosolic HMGB1." (PMID 32382012, 2020). "As an anti-inflammatory drug and an effective inhibitor of inflammatory mediator late high mobility group box 1 (HMGB1), EP has also been proved to have anti-tumor effects in various tumors in recent years." (PMID 32742812, 2020).
tumor (continued). "However, codeletion of Hmgb1 in the autophagy-deficient liver results in delayed tumor development via an unknown mechanism independent of its usual role in inflammation and fibrosis." (PMID 32382012, 2020). "TMQ0153 treatment significantly stimulates the release of HMGB1, leading to immunogenic cell death (ICD), which is a form of chemotherapy-induced tumor cell death." (PMID 32660524, 2020). "The expression levels of HMGB1 and CRT protein in orthotopic CT26 tumour mice treated with the PEG-TECM-NS/OLE were obviously elevated, which agreed well with the immunofluorescence analysis results." (PMID 33009382, 2020). "Here we report that, after NB-PDT, the cytoplasmic DAMP HSP70 was detected on the cell membrane of tumor cells and the nuclear DAMP HMGB1 was found in the cell cytoplasm." (PMID 32326519, 2020). "HMGB1 then binds to platelets via toll-like receptor 4 (TLR4) to mediate cell adhesion and enables tumor cell survival and metastasis." (PMID 33353113, 2020). "We showed that HMGB1 and its dominant receptor RAGE positively affect the proliferation of tumor cells, likely via a paracrine mode." (PMID 32382012, 2020). "These molecules work as stimuli to derive the recruitment of DC infiltration into the tumor microenvironment, resulting in the engulfment (stimulated by CRT) and presentation (stimulated by HMGB1) of TAA by DCs." (PMID 34138119, 2020). "In addition, a study in transgenic mice with a targeted genomic ablation of HMGB1 in NK cells, clearly demonstrated the crucial role of this cytokine in NK development, IL-2-induced proliferation, NK cell bioenergetics and diverse NK functions, including tumor control." (PMID 32664328, 2020). "A large number of oncogenes as target genes of miR-505 in tumor cells, including TGF-α, HMGB1, FZD4, IGF1R, WNT7B, MAP3K3, NRCAM, and RUNX2, have been recognized as direct target genes of miR-505." (PMID 33520999, 2020). "HMGB1 is also dependent on the immune receptor Tim-3 to induce angiogenic VEGF secretion and participate in tumor angiogenesis." (PMID 32660524, 2020). "Other paracrine mediators, such as the release of the tumor cell death factor high-mobility group box-1 (HMGB1), have been shown to bind to TIM-3 on DCs and impair their ability to orchestrate anti-tumor immune responses." (PMID 31921140, 2019). "Total RNA and protein were then extracted from tumor xenografts, and NNT-AS1, miR-496, and HMGB1 protein expression were measured." (PMID 31848324, 2019). "The mice received 20 Gy X-ray irradiation, and were randomized 7 days later to receive surrounding tumor injections of PBS, HMGB1, and HMGB1 antibody every 2 day for 2 weeks." (PMID 31558702, 2019). "HMGB1 and HSP70 released in the tumor bed from overexpressed tumor cells following irradiation were reported to trap injected eMIP and work together with eMIP in complexes." (PMID 31717914, 2019). "The interaction between high-mobility group box 1 protein (HMGB1) and receptor for advanced glycation end products (RAGE) is important for tumor cell growth." (PMID 31100066, 2019). "Acetylated HMGB1 (Ac-HMGB1) secreted by geminin-overexpressing cells activates RAGE and CXCR4 expression on mesenchymal stem cells (MSCs) located in tumor stroma." (PMID 31844158, 2019). "Supporting this concept, the circulating level of HMGB1 was found to be highly elevated in patients with HCC and significantly correlated with tumor size and other clinicopathological features." (PMID 31731454, 2019). "Tumour antigens and DAMPs such as CRT, HSP70, HSP90, and HMGB-1 are likely to be released from boiling histotripsy-treated tumour cells at the HIFU focus in situ, followed by the generations of pro-inflammatory cytokines and chemokines." (PMID 31227775, 2019). "Compared to non-tumor tissues (N), a variety of factors like TGF-β1, TGF-β2, HMGB1, PVR, nectin-2, galectin-9, PD-L1, PD-L2, and MICA/MICB were significantly higher in the tumor tissue (T)." (PMID 31234517, 2019).
tumor (continued). "This analysis indicated that tumor xenografts derived from siNNT-AS1–transfected T24 cells featured lower NNT-AS1 (P < 0.05) and HMGB1 protein expression (P < 0.05) as well as higher miR-496 expression (P < 0.05) compared with the siNC group." (PMID 31848324, 2019). "Mechanistically, tumor cells treated with β-lap triggered ICD and increased tumor immunogenicity by the release of HMGB1." (PMID 31324798, 2019). "However, the specific role of HMGB1 in tumor development and progression remains largely unknown." (PMID 31410208, 2019). "The resulting tumor damage led to the release of the DAMP signaling molecules hsp70, HMGB1, and ATP." (PMID 31426515, 2019). "In tumor, TIM-3 was highly expressed on tumor infiltrating DCs and can compete with nucleic acid binding to HMGB1, therefore dampening anti-tumor immunity mediated by nucleic acids." (PMID 31690319, 2019). "Secreted HMGB-1 activates TLR9, which encourages tumor progression via activation of related intracellular growth signaling pathways, involving phosphorylation of p38, Stat3, JNK and p65 of NF-kB." (PMID 31474975, 2019). "Treatment of MEFs and tumor cells with autophagy inhibitors prevents LC3 puncta formation and HMGB1 translocation." (PMID 31379812, 2019). "The specific inhibition of extracellular HMGB1 with glycyrrhizin (GLZ) improved radiation response in tumors by the attenuation of recruitment of MDSCs and TAMs and shifting the tumor immune microenvironment towards anti-tumoral response." (PMID 31015520, 2019). "HMGB1 treatment resulted in significant upregulation of stem cell markers (Oct4 and Nanog) and CD133+ cell proportion in fresh tumor tissues, which were abrogated by silencing TLR2, YAP, or HIF-1α." (PMID 31558702, 2019). "Tumor hypoxia promotes NET formation within the metastatic site, and the NETs release the High mobility group box 1 (HMGB-1) protein." (PMID 31474975, 2019). "Our data confirmed that a marked increase in HMGB1 was observed in plasma from ESCC blood and tissue, and HMGB1 significantly accumulated in tumor-derived exosomes." (PMID 30796203, 2019). "The extracellular release of HMGB1 and ATP attracts and activates APCs, whereas CRT exposure on the surface of dying tumor cells serves as an “eat-me” signal for phagocytes." (PMID 31861079, 2019). "HMGB1 enhanced release of CXCL12 from stromal cells, which subsequently induced robust infiltration of neutrophils and dendritic cells into the tumor, resulting in invasive cancer clearance." (PMID 30744691, 2019). "eMIP works with alarmins such as high mobility group box 1 (HMGB1) and heat shock protein 70 (HSP70) released from overexpressed tumor cells by irradiation." (PMID 31058025, 2019). "The HMGB1 protein stimulates HCC cells to generate oncomiRs, which inhibit tumor suppressors such as RECK and TIMP3, and promote HCC malignancy." (PMID 29651425, 2018). "In necrotic cells, HMGB1 can be released from the nucleus to the extracellular space to regulate inflammation, angiogenesis, and EMT, which is required for initiating tumor invasion and metastasis." (PMID 29636841, 2018). "On the other hand, extracellular HMGB1 is recognized as a prototypical DAMP, which has the protumorigenic role of promoting tumor progression." (PMID 30526680, 2018). "We determined protein expression of HMGB1 and HIF-1 alpha in the RCC panel by immunohistochemistry (IHC) and their levels in the tumor xenograft panel were quantified using OSANO software." (PMID 30123419, 2018). "RAGE ligands, AGE, HMGB1, and S100 protein family, secreted from cancer cells and leukocytes interact with RAGE and other receptors and regulate further tumor progression." (PMID 29529089, 2018). "Tumor cells release soluble mediators like ADP, thromboxane A2 (TXA2), or high-mobility group box 1 (HMGB1), which ligates with toll-like receptor 4 (TLR4) to instigate a local platelet activation." (PMID 30305116, 2018).
tumor (continued). "Previous studies have shown that HMGB1 can interact with various DNA repair proteins (e.g., RAG and XPA) to address DNA damage repair and to inhibit tumor cell apoptosis." (PMID 30157958, 2018). "We used immunohistochemistry to examine the subcellular localization and expression levels of HMGB1 and HMGN1, as well as tumor CD3+, CD8+, FOXP3+ lymphocyte infiltration, and the expression of immune inhibiting molecules PD-1/PD-L1." (PMID 30619746, 2018). "Another key factor modulating activation of an immune response, high mobility group box 1 (HMGB1), is released from tumor cells upon exposure to x-ray or carbon-ion radiation." (PMID 29556198, 2018). "OxP treatment significantly increased HMGB1 and CRT staining within the orthotopic CT26-FL3 tumor tissues, a result that mirrors the in vitro findings." (PMID 29884866, 2018). "Recent studies have shown that HMGB1 can participate in cell differentiation, migration, regeneration, and mediation of inflammation, particularly in binding to RAGE, to affect tumor growth, invasion, and metastasis." (PMID 29850505, 2018). "HMGB1 plays an important role in regulating epithelial-mesenchymal transition (EMT), which initiates tumor invasion and metastasis." (PMID 29636841, 2018). "ICD stimulates emission of DAMPs, including adenosine triphosphate (ATP), high mobility group box 1 (HMGB1), and calrecticulin (CALR), which initiates antigen uptake, maturation, activation, and recruitment of endogenous DCs in the tumor." (PMID 30568653, 2018). "Tumor growth rates increased over passages for the low secretor group and diminished in PDX with high HMGB1 serum levels." (PMID 30123419, 2018). "Here we show that Hemidesmus treatment induces tumor cell cytotoxicity characterized by surface expression of calreticulin, increased HSP70 expression and release of ATP and HMGB1." (PMID 29849952, 2018). "The mechanism of tumor cell survival, expansion and metastasis is binding to TLR-2, TLR-4, TLR-9 and RAGE, which mediates HMGB1-dependent activation." (PMID 30526680, 2018). "Tumor cell-released HMGB1 interacts with TLR4 on platelets, mediating the interaction of tumor cells and platelets to promote metastasis." (PMID 29636841, 2018). "Diminished nuclear and total cellular expression of HMGB1 in PDAC patients correlates with poor overall survival, supporting intracellular HMGB1 as a novel tumor suppressor with prognostic and therapeutic relevance in PDAC." (PMID 28374746, 2017). "In human tumor biopsies maintained in ex vivo culture, EnAd mediated release of pro-inflammatory mediators such as TNF-α, IL-6, and HMGB1." (PMID 28345021, 2017). "Recent studies have verified that HMGB1 is overexpressed in various cancers and regulates EMT, tumour progression, and malignant transformation." (PMID 28727734, 2017). "Inhibition of the HMGB1-RAGE interaction suppresses activation of MAP kinases, which are the important molecular effector mechanisms linking to tumor progression." (PMID 28969092, 2017). "Through direct interaction with HMGB1, TIM-3—which is highly expressed on tumoral DCs—circumvents the stimulatory effects of nucleic acids in tumor immunity." (PMID 28300768, 2017). "On the other hand, HMGB1 increases MDSC (myeloid-derived suppressor cells)—macrophage crosstalk and production of IL-10, thereby skewing macrophages toward a type II tumor—promoting phenotype." (PMID 28196513, 2017). "In many tumor isolates AR42 and valproate also promoted the extracellular release of the immunogenic protein HMGB1." (PMID 29137331, 2017). "In some studies, the interaction of extracellular HMGB1 and RAGE induces NF-кB activation or MAPK signaling pathway to promote tumor cell invasion and metastasis." (PMID 28969092, 2017). "High-mobility group box 1 (HMGB1) is a nuclear protein that is known to be secreted into extracellular fluids from injured cells, activated macrophages, and tumor cells." (PMID 28536706, 2017).
tumor (continued). "Similar findings regarding HMGB1 extracellular release were made with AR42 and sodium valproate in multiple other tumor types." (PMID 29137331, 2017). "Exogenous HMGB1 and RAGE coordinately contribute to tumor cell ATP production and subsequent cell proliferation in a time- and dose-dependent manner." (PMID 28969092, 2017). "HMGB1 and its receptor RAGE are pivotal factors in the development and progression of many types of tumor, including HCC." (PMID 28403886, 2017). "Another proinflammatory multifunctional protein called HMGB1 binds RAGE and acts as a transcriptional regulator for inflammatory response and tumor progression." (PMID 27769286, 2016). "Thus, HMGB1 could act as an autocrine/paracrine tumor-growth factor in cancer." (PMID 27836008, 2016). "Univariate analyses also indicated tumor size, tumor differentiation, BCLC stage, peritumoral HMGB1 expression, and peritumoral TAM count to be prognostic factors for RFS." (PMID 27836008, 2016). "Extracellular HMGB1 in turn binds to RAGE and TLR4 and activates proinflammatory signaling pathways such as NF-κB and inflammasome, thus accelerating tumor growth and metastasis." (PMID 26925422, 2016). "IL RB resulted in necrosis of tumor cells and the release of High Mobility Group Box 1 (HMGB1), with increased dendritic cell (DC) infiltration into draining lymph nodes and the activation of tumor-specific T cells." (PMID 27177220, 2016). "The released HMGB1 by dying cancer cells can bind Toll-like receptor (TLR-) 4 and promote the processing and presentation of tumor antigens by DCs." (PMID 27933272, 2016). "Passively diffused proteins were then IPd using an anti-HMGB1 antibody, which showed almost equal amounts of HMGB1 in naïve HME and GemOE tumor cell lines." (PMID 26989079, 2016). "In chemotherapy and radiotherapy, treated cancer cells release ATP and/or High-Mobility Group Protein B1 (HMGB1) and activate DCs via the inflammasome or TLR4 pathways, which in turn contributed to activation of anti-tumor T cells." (PMID 27854240, 2016). "HMGB1 has been known to have important roles not only as DAMP, but also in cancer cell migration, metastasis, angiogenesis and tumor growth." (PMID 27494867, 2016). "In fact, HMGB1 released following chemotherapy-induced cell death activates DCs via the TLR4-MyD88 axis, which leads to the induction of anti-tumor T-cell immunity." (PMID 27172902, 2016). "PDT with G-chlorin directly kills tumor cells by inducing necrosis and/or apoptosis via ROS production, in such a way that the dying cells expose CRT and release HMGB1, thereby indirectly activating immune effectors." (PMID 27363018, 2016). "In BxPC-3 tumor cells treatment with two of the used TLR ligands as well as LPS resulted in increased Bcl-xL expression (ODN: ROD = 109%, LPS: 140%, and HMGB1: 175%) (right)." (PMID 27941651, 2016). "HMGB1 released in the TME induces expression of proangiogenic factors such as vascular endothelial growth factor (VEGF) and their receptors in tumor endothelial cells (EC) through RAGE mediated NF-κB signaling." (PMID 26925422, 2016). "In GSE30219, HMGB1 expression in ADC and SCC was found to be significantly different (P=0.000); it was also found to be significantly different in tumor size (T stage, P=0.000), lymph node involvement (N stage P=0.000) and distant metastasis (M stage P=0.022)." (PMID 26840258, 2016). "Multivariate analyses indicated peritumoral HMGB1 expression (p = 0.014) and TAM count (p = 0.037), as well as tumor differentiation (p = 0.026), to be independent significant prognostic factors for RFS." (PMID 27836008, 2016). "Thus, we examined whether HMGB1 mediates tumour cell death during an antitumour immune response." (PMID 26948869, 2016). "Next, the expression and subcellular localization of HMGB1 protein were detected by immunohistochemistry (IHC) in a series of 30 BUC tissues and paired adjacent non-tumour tissues." (PMID 26239046, 2015).